HIF1A (hypoxia inducible factor 1 subunit alpha)
Diseases named in the same sentence as HIF1A in open-access papers (continued):
Sharing a sentence is not in itself a finding about the gene and the disease.
cancer (continued). "HIF-1α exerts an important function in cellular adaptation to hypoxia by activating multiple cancer signaling pathways, including phosphoinositide 3-kinase (PI3K)/Akt/mammalian target of rapamycin (PI3K/Akt/mTOR) and ERK/MAPK." (PMID 36080483, 2022). "Currently, HIF-1α is widely regarded as the key inducing factor of the Warburg effect, and some lincRNA disorders in cancer mediated by HIF-1α have been identified." (PMID 36124026, 2022). "Understandably, increased ROS results in increased expression of HIF1a and its target genes as well as increased glycolysis, thus promoting the Warburg effect and subsequent cancer progression." (PMID 36200262, 2022). "HIF-1α mediates the chemoresistance features of cancer cells through multiple and interconnected mechanisms." (PMID 35814435, 2022). "These combine NPs were effectively internalized in SCC-7, BT-474, and SH-SY5Y cancer cells, greatly reduced HIF-1α expression under hypoxic conditions in tested cancer cells and induced synergistic cancer cell apoptosis." (PMID 36559200, 2022). "ADCK2 depletion suppressed tumor necrosis factor α (TNFα)-induced hypoxia-inducible factor-1 (HIF-1α) stability in cancer cells." (PMID 36439873, 2022). "Enhanced HIF-1α activity in cancer cells has been shown to increase fatty acid uptake in response to hypoxia." (PMID 36329893, 2022). "In cancer cells, HIF-1α increases Programmed death-ligand 1 (PD-L1) expression and cytokines secretion (i.e., VEGF) thereby promoting tumor associated macrophages (TAM) accumulation and immune escape." (PMID 36359304, 2022). "It would be interesting to determine what controls the basal level of viperin expression in cancer cells with the following questions in mind: (a) Do the basal levels of viperin correlate with the basal levels of HIF-1α expression?" (PMID 36519538, 2022). "This leads to suppression of mitochondrial biogenesis and lower oxygen consumption in HIF-1α over expressed cancer cell." (PMID 36014432, 2022). "The amount of HIF-1α protein detected with the ELISA in all cancer cell lines in the control normoxia was relatively low compared to hypoxic conditions." (PMID 35396948, 2022). "HIF-1α enhances the activity of Snail and Twist and then reduces E-cadherin expression, thereby promoting invasion, a cancer stem cell-like phenotype, and chemoresistance." (PMID 36238299, 2022). "Hypoxia participated in different physiological disorders, such as IRI, diabetic vasculopathy, and even cancer through the manipulation of HIF-1α-related pathways." (PMID 35605218, 2022). "Evidences suggest that hypoxia is one of the hallmarks of malignant tumors and SIRT1 being a downstream target of HIF-1α is observed to be upregulated in OvCa, thereby conferring cancer stem cell-like properties." (PMID 35496046, 2022). "HIF-1α silencing inhibits the growth and invasion of cancer cells and induces an increased rate of apoptosis in vitro." (PMID 35664561, 2022). "Studies have shown that EPA and DHA have potent anti-angiogenic effects on cancer cells via the inhibition of HIF-1α, VEGF, and VEGFR production." (PMID 36547898, 2022). "Researchers used SPION-NPs coated with thiolated chitosan (ChT) and trimethyl chitosan (TMC) and functionalized with hyaluronate (H) and TAT peptide for delivery of siRNA molecules against STAT3 and HIF-1α to cancer cells both in vivo and in vitro." (PMID 36532768, 2022). "This is thought to occur following an exposure of cancer cells to a hypoxic environment, which activates hypoxia-inducible factor (HIF-1α) and sonic hedgehog-GLI signaling." (PMID 36010899, 2022). "A study on hepatocellular carcinoma demonstrated that releasing chemokines by cancer cells is regulated by HIF-1α." (PMID 36292613, 2022). "In this study, we demonstrate that targeting HIF-1α can achieve such an effect in preclinical models of cancer." (PMID 35239514, 2022).
cancer (continued). "They assessed the impact of B[a]P (1.5 μM and 25 μM) on A549 and MCF-7 cancer cells and noticed an increase in the ROS level and changes in HIF-1α and HO-1 in tested cancer cells." (PMID 35683027, 2022). "Transcription factors regulating glucose homeostasis (HIF-1α) correlate with MDR1 expression in aggressive cancer." (PMID 36297616, 2022). "The activation of the EMT upregulates the expression of EMT-related transcription factors and mesenchymal markers through TGF-β and Wnt signaling, MMPs, and HIF-1α, increasing the invasiveness of cancer cells." (PMID 36547898, 2022). "HIF-1α has a significant impact on angiogenesis, plays an important role in cell function, and promotes the adaptation of cancer cells to the conversion from an aerobic to anaerobic metabolism." (PMID 35205136, 2022). "On the basis of the findings of this study, the authors would like to mention that PHD-2 nuclear localization plays a critical role in the regulation of HIF-1α, as well as the development and progression of cancer." (PMID 35592530, 2022). "HIF-1α mediates metabolic switching by upregulating glucose transporters and glycolytic enzymes, favoring the adaptation of cancer cells to hypoxia and eventually inducing drug resistance." (PMID 35127685, 2022). "The prevention resulted in the binding of HIF1α with a hypoxia-response element, thus inducing the anti-cancer element of A. paniculata." (PMID 35682652, 2022). "Immunohistochemical studies have shown that HIF-1α overexpression is present in most cancers, and clinical studies have also revealed an inverse correlation between HIF-1α expression and overall patient survival." (PMID 36077667, 2022). "At the same time, lactate release of glycolysis into the TME in cancer cells also upregulated HIF-1a expression in TAMs, resulting in increased glycolysis and the M2-like state." (PMID 35874739, 2022). "An increased expression of HIF-1α is connected with the progression of different cancers, promotion of angiogenesis, neovascularization, and sustained inflammation." (PMID 36555323, 2022). "In certain cases, HIF-1α triggers apoptosis in cancer cells via regulation of pro-apoptotic, anti-apoptotic and apoptotic proteins." (PMID 36014432, 2022). "The metabolic switch pertinent to accelerated glycolysis in cancer cells results from increased expression of oncogenes, primarily c-Myc and HIF-1α." (PMID 36531060, 2022). "have reported that APEX1 interacts with HIF-1α under hypoxia and inhibition of APEX1 will result in decreased HIF-1α–mediated induction of carbonic anhydrase IX, which will inhibit viability of cancer cells." (PMID 35311089, 2022). "HIF-1α overexpression has been described in a variety of human cancers, and targeting HIF-1α is yet another treatment way to overcome drug resistance." (PMID 35631634, 2022). "Hypoxia-inducible factor-1α (HIF-1α) reinforces all hallmarks of cancer and donates cancer cells with more aggressive characteristics at hypoxic niches." (PMID 35681691, 2022). "Hypoxia-inducible factor-1a (HIF-1a), overexpressed in advanced cancers, in part, due to aberrant vascularization, often directly or indirectly reprograms the cancer-associated fibroblasts, macrophages, and extracellular matrix." (PMID 35216362, 2022). "In case of MCF-7 cancer cell line treated with all chemotherapeutic agents, the combined chemoradiotherapy also showed a reduction of HIF-1α level when the radiation dose has been doubled (i.e., from 5 to 10 Gy)." (PMID 35396948, 2022). "This pathway seems to be predominant in cancer subjected to hypoxia, displaying constitutive hypoxia-inducible factor 1 alpha (HIF1α) activation, or have defective mitochondria and has been confirmed to occur also in vivo." (PMID 36428783, 2022). "Ole’s potential to impact PARPs, the Bax/Bcl2 ratio, the P38 MAPK pathway, HIF-1α, and the Akt and Jnk pathways disrupts cancer’s anti-apoptotic and angiogenic capabilities." (PMID 36013319, 2022).
cancer (continued). "On the basis of its important functions in cancers, HIF-1α is an important therapeutic target for cancer treatment." (PMID 35906392, 2022). "In this study, we sought to study HIF1A cofactors and how they connect to the role of HIF1A as a master regulator of a cancer cell’s response to hypoxia." (PMID 36347941, 2022). "HIF-1α is predominantly involved in the early stages of cancer, whereas HIF-2α is actively involved in the later stages." (PMID 36376931, 2022). "Consistent with the in-vitro experiments, HIF-1α knockdown induced decreases in cancer growth and abrogated the functions of circDNMT1 (–C)." (PMID 35712504, 2022). "This is consistent with our data showing that cancer cell-induced lipolysis is blunted in the HIF1α-defiecient adipocytes, therefore the availability of lipids from these cells is reduced." (PMID 36329893, 2022). "HIF-1α also favors an immunosuppressive TME by reinforcing other cancer-promoting immune cell functions, including MDSCs and M2-like macrophages." (PMID 36200045, 2022). "To validate HIF-1α as a therapeutic target for a small cell population or an early stage of cancer progression prior to the creation of a hypoxic core, we established in vivo models using a doxycycline-inducible sh-Notch1 U251-MG cell line and chetomin." (PMID 36183290, 2022). "It is also evident that in cancer cells HIF-1α induces the expression of monocarboxylate transporter 4 MCT4, a plasma membrane binding transporter, which is known for its lactate extruding activity followed by pyruvate to lactate conversion." (PMID 36014432, 2022). "This process is similar to aerobic glycolysis, in which HIF-1α shifts cancer cells’ metabolism from OXPHOS to glycolysis." (PMID 36292613, 2022). "For example, HIF1A-dependent increases in PD-L1 expression were observed when human cancer cells were exposed to hypoxia for 24 h." (PMID 35659268, 2022). "Based on our findings, UBE2C expression mediates HIF‐1α activation, increasing glycolysis pathway activation and the invasion/migration abilities of cancer cells." (PMID 35615976, 2022). "Hypoxia-inducible factor 1α (HIF-1α)-induced extracellular matrix remodeling by fibroblasts promoted the invasion and metastasis of cancer cells." (PMID 35155430, 2022). "During the cancer process, cancer cells experience oxidative stress, which enhances HIF-1α expression and stimulates TGF-α and Caveolin (Cav1) protein loss, downregulating TGF-α; moreover, stromal cells undergo autophagy and become CAFs." (PMID 36059650, 2022). "In a hypoxic environment, activated HIF-1α promotes cancer migration in multiple ways, such as promoting EMT-related signaling, regulating the alignment of collagen fibers, and mediating the leakage and compression of blood and lymphatic vessels." (PMID 36439690, 2022). "In the cancer cells, HIF-1α not only stimulates the induction of GLUT1, GLUT3 and GLUT4 transporter to uptake blood glucose, but also enhances glycolytic breakdown of intracellular glucose by transactivating phosphofructokinase 1 (PFK1) and aldolase." (PMID 36014432, 2022). "The reported findings suggest that succinate acts in an autocrine and paracrine manners to drive cancer metastasis via the SUCNR-1 → PI-3K → Akt → HIF-1α signaling pathway." (PMID 36344992, 2022). "Multiple studies suggested that HIF-1α served as a key transcriptionally regulatory element for PD-L1 upregulation in a range of cancers." (PMID 35295999, 2022). "HIF-1α is expressed and stabilized in immune cells via hypoxia or other factors, such as inflammation, cancer, and infectious micro-organisms." (PMID 36496973, 2022). "The main reason for selecting HIF1A (encoding the HIF-1α protein) in the cDNA microarray for further study was that HIF-1α has shown great importance in guiding clinical cancer therapy." (PMID 35236823, 2022).
cancer (continued). "Giving its effect in regulating LVBU and urea cycle in cancer, reemphasizing the need of developing HIF-1α inhibitors in cancer therapeutic design is necessary." (PMID 35906392, 2022). "In such case, HIF-1α-induced transcription of CKAP2 would add a further layer of control to fine-tune the expression of CKAP2 in cancer." (PMID 35853854, 2022). "Copper promotes the adaptation of cancer cells to the hypoxic environment by reducing degradation and increasing HIF-1α stability." (PMID 36419894, 2022). "2-ME, an HIF-1α inhibitor that is used as an anti-cancer drug, inhibited RISIs and repaired damaged skin vessels." (PMID 35456989, 2022). "Topotecan has shown to inhibit HIF-1α protein amassing in human cancer cell lines independently of replication-mediated DNA damage, suggesting the existence of an alternative mechanism of action to the cytotoxic one." (PMID 36362482, 2022). "The expression of HIF-1α is positively correlated with the malignancy and poor prognosis of cancers." (PMID 36059955, 2022). "The cytoprotective properties are detrimental in oncology, for example, an upregulation of HIF1-α has been demonstrated in vivo, also reduced NK cell activity and increased migration of cancer cells." (PMID 36431218, 2022). "In WI‐38 fibroblasts, there was significant upregulation of HIF1α when the cells were cocultured with the CASQ2 o/e cancer cells." (PMID 34743414, 2022). "HIFs, such as HIF1α, HIF2α, and HIF3α, binds to the target gene promoter to promote its transcription, thus accelerating cancer cell migration, proliferation, and invasion." (PMID 35635094, 2022). "There are limited studies on the use of KUSC-5001 as a HIF-1α inhibitor, so it needs to be further explored as a possible anti-cancer agent." (PMID 36139386, 2022). "Since AMPK is a key regulator of cellular energy metabolism, ROS redox balance and the interaction between HIF-1α and AMPKα have been reported in cancer cells." (PMID 34987647, 2022). "Here, we discuss a few natural products which have an inhibitory role on HIF-1α and are able to regulate different cancer progressions." (PMID 36014432, 2022). "HIF-1α promotes cancer growth in low oxygen environments and the mechanisms through which HIF-1α helps BCSCs are described in low oxygen environments through mechanisms described in the previous section." (PMID 35805056, 2022). "Many reports indicated that pyruvate dehydrogenase inactivation and lactate dehydrogenase activation occurred in hypoxia assisted glycolysis of cancer cells are high in correlation to activation of HIF‐1α, and C‐Myc activation." (PMID 35079624, 2022). "Lactate dehydrogenase (LDH), which is commonly activated by oncoproteins like cMyc, HIF-1α, and mTOR in cancer cells, converts pyruvate to lactate while simultaneously oxidizing NADH to NAD+." (PMID 36419156, 2022). "The overall effects of HIF-1α under hypoxic conditions have been extensively studied and have revealed their involvement in the conventional oncogenic responses of various malignant tumors." (PMID 36183290, 2022). "Metformin treatment downregulates immune checkpoint expression and glycolytic cancer flux in a HIF-1α inhibition-dependent manner, thereby improving ICB therapy." (PMID 36200045, 2022). "Interestingly, the main mediator of hypoxia, HIF-1α, was found as an exosomal package in a transcriptionally active form in nasopharyngeal carcinoma cell-derived exosomes, where its expression promoted cancer invasive potential in association with latent membrane protein 1 (LMP1)-positive exosomes." (PMID 36233088, 2022). "Overexpression of HIF-1α is related to a poor prognosis and treatment resistance in cancer patients." (PMID 35565972, 2022). "The extent of information about the molecular mechanisms by which HIF-1α leads to hypoxic adaptation in cancer is increasing at a great pace." (PMID 35681691, 2022).
cancer (continued). "During its hypoxia-induced stabilization, HIF-1α, which typically disintegrates instantly, is accumulated in the cells, playing the maestro in coordinating all the subsequent evolution of cancer (level A)." (PMID 36276103, 2022). "The effects of hypoxia in cancer cells are well established as metabolic adaptations driven by HIF-1α provide a selective advantage for cancer cells in the low oxygen environment." (PMID 36329893, 2022). "As well, it inhibits the VEGF by modulating the activity of hypoxia-inducible factor 1α (HIF-1α) and NF-kB factor; so, as a result, it inhibits the cancer angiogenesis." (PMID 35956766, 2022). "Crosstalk between NF-κB and HIF-1α signaling cascades elevates inflammatory response in cancer by transcribing different downstream modulators such as IL-6, MMP9, and COX2." (PMID 36014432, 2022). "HepG2 cancer cell line treated with all chemotherapeutic agents showed a reduction in the level of HIF-1α when the radiation dose was doubled (i.e., from 5 to 10 Gy)." (PMID 35396948, 2022). "These bindings promote HIF-1α synthesis via the PI3K/AKT signaling cascade resulting in angiogenesis in cancer." (PMID 36014432, 2022). "Over the past two decades, tremendous efforts have been made to develop HIF-1α inhibitors to prevent the spread of cancers." (PMID 36080483, 2022). "This in turn inhibits the transcription of HIF-1α, thereby promoting an adaptive metabolic switch in cancer cells known as the “anti-Warburg effect”." (PMID 35495117, 2022). "As a HIF-1α inhibitor, curcumin (diferuloylmethane) has been assumed to decrease glucose uptake in many cancers, such as lung, cervical, prostate, and breast cancers." (PMID 35992779, 2022). "These facts confer a pivotal relevance to mir-210, which acts as an oncomir, and highlights the importance of HIF-1α in cancer progression." (PMID 35741024, 2022). "Wen and colleagues demonstrated that the long non-coding RNA DANCR promotes the stability of HIF-1α mRNA, supporting cancer cell invasion and migration." (PMID 35565420, 2022). "Other than these, a variety of mechanisms regulate HIF-1α mediated cancer stem cell propagation and maintenance." (PMID 36014432, 2022). "That indicates that PBLD blocks angiogenesis while avoiding the increased HIF-1a expression in cancer cells resulted from anti-angiogenesis induced hypoxia." (PMID 35140333, 2022). "It participates in cancer metastasis by targeting HIF‐1α/EMT‐related signaling pathways and is a potential therapeutic target." (PMID 35028969, 2022). "On the other hand, compared with primary tumors, HIF–1α protein expression in metastatic tumors is increased, while hypoxia signaling in CTCs predicts reduced overall survival in patients with cancer metastasis." (PMID 36059616, 2022). "Hypoxia–inducible factor 1 alpha (HIF–1α) is overexpressed in human cancers, partly as a result of hypoxia within tumors." (PMID 36059616, 2022). "Hypoxia-inducible factor-1α (HIF-1α) is a transcription factor that regulates cancer growth, metabolism, cell proliferation, migration, angiogenesis, and apoptosis." (PMID 35740392, 2022). "The upregulated SIRT1 was shown to increase the deacetylation-dependent stability of HIF-1α protein, thus promoting glycolysis and chemoresistance in the recipient normoxic cancer cells." (PMID 36176760, 2022). "Since the vascular endothelial growth factor (VEGF)representsthe main target of HIF-1α, we measured its expression in theprostate cancer cells treated with the dendrimers." (PMID 36445323, 2022). "This newly discovered function of PFKFB4, coupled with its cancer specificity, provides a new strategy for inhibiting HIF-1α in cancer cells." (PMID 36115843, 2022). "HIF-1α, the main transcription factor involved in hypoxia, is overexpressed in many types of cancer." (PMID 36139362, 2022).